NKILA (NF-kappaB interacting lncRNA)
Diseases named in the same sentence as NKILA in open-access papers (continued):
Sharing a sentence is not in itself a finding about the gene and the disease.
tumor (84 papers, 2016 to 2025). "It is indicated that compared with the group with high NKILA expression level, the group with low NKILA expression level was easily affected by the increased risk of tumour size." (PMID 38243168, 2024). "NKILA lncRNA, for example, aids tumor immune evasion by making T cells more susceptible to activation-induced cell death." (PMID 35710698, 2022). "In this study, they also found that knockdown of NKILA strikingly reduces the expressions of E‐cadherin, which mediates the loss of cell adhesion, a prerequisite for the infiltration and metastasis of tumor cells." (PMID 32249459, 2020). "Chi-square analysis revealed that decreased NKILA expression in HCC was significantly associated with larger tumor size and positive vascular invasion." (PMID 32015685, 2020). "All these data suggested that NKILA expression was significantly downregulated in ESCC tumor tissues and implicated NKLIA in ESCC tumorigenesis and progression." (PMID 29379981, 2018). "More importantly, blockade of NF-κB activation by NKILA via inhibition of IκBα phosphorylation was associated with its tumor suppressive roles." (PMID 29348395, 2018). "Specifically, we found that decreased NKILA expression was strongly associated with large tumor size and high TNM stage." (PMID 29348395, 2018). "The results showed that the downregulation of NKILA were significantly associated with advanced T stage (p = 0.01), larger tumor size (p = 0.019), advanced TNM stage (p = 0.048) and lymph node metastasis (p = 0.002)." (PMID 28412955, 2017). "All these data suggested that the expression of NKILA was significantly downregulated in NSCLC tumor tissues and implicated in the tumorigenesis and metastasis of NSCLC." (PMID 28412955, 2017). "Because increased NF-κB activity is associated with enhanced invasiveness of tumor cells, we further detected the function of NKILA in NF-κB activation." (PMID 27613832, 2016). "Recently, a study concerning OS revealed that NKILA, a tumor suppressor that interferes with the NF-κB pathway in various cancer types, has lower expression levels in OS tissues and is associated with metastasis, tumor size, and the Enneking stage." (PMID 38516191, 2024). "The expression level of NKILA was positively associated with the tumor apoptosis level (P < 0.001)." (PMID 31430288, 2019). "Furthermore, NKILA expression is negatively associated with tumor metastasis in patients with NSCLC." (PMID 28412955, 2017). "In addition, with regard to the clinical prognosis, the results indicated that the group associated with low NKILA expression level had a heightened risk of advanced clinical stage, poor histological grades, positive lymph node metastasis, and extended tumor invasion depth." (PMID 32851072, 2020). "Loss- and gain-of-function assays showed NKILA could act as a tumor suppressor in ESCC." (PMID 29348395, 2018). "Next, we constructed a mouse ICC model using HuCCT1 or RBE cells and found that NKILA silencing inhibited tumor growth compared to KD‐NC + OE‐NC, which was reversed by MTX1 overexpression (p < 0.05)." (PMID 41498025, 2025). "NKILA (NF-κB Interacting LncRNA) is another lncRNA demonstrated to have a role in the blockage of tumor growth and the inhibition of metastasis in several types of neoplasms." (PMID 41020820, 2025). "Direct CTL functional regulation is exemplified by the lncRNA NKILA-mediated pathway which promotes tumor immune evasion by directly sensitizing CTLs to activation-induced cell death (AICD)." (PMID 41409273, 2025). "A number of lncRNAs discussed in previous sections, such as SNHG17, MALAT1, XIST, SBF2-AS1, NKILA, and Linc-pint, have been shown to regulate tumor behavior in preclinical studies through their interaction with the TGFβ pathway." (PMID 41437175, 2025). "Clinically, NKILA overexpression in tumor-specific CTL and TH1 cells correlates with shorter patient survival and increased apoptosis." (PMID 37670938, 2023).
tumor (continued). "In contrast, other lncRNAs such as the growth arrest-specific transcript 5 (GAS5), the maternally expressed gene 3 (MEG3), and the NF-kB interacting lncRNA (NKILA) function as tumor suppressors, inhibiting proliferation and tumor growth when up-regulated." (PMID 36827545, 2023). "LncRNA NKILA has demonstrated the ability to initiate apoptosis in tumor-specific T cells, thereby impeding their capacity to infiltrate the tumor, leading to tumor immune evasion." (PMID 37696973, 2023). "They evidenced that the downregulation of the lncRNA NKILA and NBAT1 are linked to tumor size, whereas the blood concentration of H19 and SPRY4-IT1 is a good parameter to discriminate between BC patients and controls." (PMID 37958880, 2023). "The NKILA lncRNA stimulates activation-induced cell death in T cells, promoting tumor immunoevasion." (PMID 37670938, 2023). "NKILA silencing enhances T cells’ resistance to apoptosis and protect the transferred T cells from tumor-mediated AICD." (PMID 37637063, 2023). "In HCC, NKILA suppresses the metastatic spread of the tumor by inhibiting NF-κB/Slug-mediated EMT in these tumor cells." (PMID 36770654, 2023). "NKILA is a tumor suppressor that affects the proliferation and metastasis of cancer cells by regulating the STAT3 pathway." (PMID 35368654, 2022). "For instance, NKILA lncRNA boots tumor immune evasion by sensitizing T cells to activation-induced cell death." (PMID 35710698, 2022). "The expression level of CCDC144NL-AS1, MNX1-AS1, TEX41, NKILA, and Z99289.2 was higher in tumor tissue." (PMID 36531020, 2022). "For example, the lncRNA NKILA promotes tumour immune escape by sensitizing T cells to activation-induced cell death." (PMID 35031063, 2022). "NKILA lncRNA can promote tumor immune evasion by sensitizing T cells to activation-induced cell death." (PMID 35603200, 2022). "Taken together, the epigenetic silencing of lncRNA NKILA was mediated by promoter DNA methylation in a tumor-specific manner in NHL." (PMID 35052468, 2022). "As a CpG island is present at the promoter region of NKILA, we postulated that NKILA is a tumor suppressor lncRNA reversibly silenced by promoter DNA methylation in NHL." (PMID 35052468, 2022). "For example, NKILA has been shown to sensitize antitumor T cells to cell death upon activation by tumor antigens." (PMID 35189921, 2022). "In immunocompromised mice, CD8 + CTLs transduced with NKILA shRNA were administered along with human breast cancer xenografts and this effectively inhibited tumor growth." (PMID 35189921, 2022). "NF-κB-interacting lncRNA (NKILA) has been identified as a tumor suppressor that regulates NF-κB activity, and its expression is decreased in various cancers." (PMID 35984196, 2022). "We found that AC022613.1, GSEC, LINC00941, and NKILA were mainly upregulated in tumor samples compared with normal samples." (PMID 35368654, 2022). "So, NKILA is considered as a tumour suppressor lncRNA for disease progression and metastasis and it acts through the NF-KappaB signalling pathways in OSCC." (PMID 36428681, 2022). "lncRNA NKILA mediates T‐cell sensitivity to tumor cell death, playing an immunosuppressive role in tumor immunology." (PMID 34250747, 2021). "A growing number of lncRNAs, such as MALAT1, NEAT1, and NKILA, have been shown to function as either tumor suppressors or oncogenes in various cancer types." (PMID 33869020, 2021). "For example, the lncRNA NKILA can induce the apoptosis of tumor-specific T cells so that they cannot penetrate the tumor." (PMID 34295338, 2021). "One study reported that tumor suppressor lncRNA NKILA hindered OSCC migration and invasion by interacting with NF-κB and ultimately lowering Twist and E-cadherin." (PMID 34885054, 2021). "NKILA was found to promote tumour immune evasion by sensitizing T cells to activation-induced cell death." (PMID 34391383, 2021). "LncRNA NKILA inhibits NF-κB activity, allowing the immune-mediated clearance of activated T lymphocytes to promote tumor immune evasion." (PMID 35071016, 2021).
tumor (continued). "LncRNA NKILA promoted tumor immune evasion by inhibiting nuclear factor κB activity to regulate T-cell sensitivity to activation-induced cell death." (PMID 33815468, 2021). "In contrast, the upregulation of NKILA expression in tumor cells significantly increased angiogenesis in U87 and A172 cell lines." (PMID 32382013, 2020). "Our results showed that the expression of NKILA was down-regulated in HCC tissues and decreased NKILA expression was significantly associated with larger tumor size and positive vascular invasion." (PMID 32015685, 2020). "lncRNA NKILA promotes cytotoxic T lymphocytes death via inhibiting NF‐κB activity and therefore promotes tumor immune evasion." (PMID 31785055, 2020). "QRT-PCR was used to analyze mouse tumor tissues and confirmed the effects of NKILA suppression by different treatment in vivo." (PMID 32382013, 2020). "The collective results of six studies reported the relationship between NKILA expression and tumor invasion depth." (PMID 32851072, 2020). "Recently NKILA, an NF-κB-interacting long noncoding RNA (lncRNA) was shown to promote tumor immune evasion by sensitizing T cells to activation-induced cell death and increasing CTL infiltration." (PMID 32754302, 2020). "Elsewhere, NKILA inhibited tumor metastasis by suppressing the NF-κB/Slug mediated ETM pathway in HCC." (PMID 32879628, 2020). "In particular, the expression of HIF-1α is upregulated in tumor cells overexpressing NKILA, and downregulated in tumor cells with low levels of NKILA expression." (PMID 32382013, 2020). "More recently, NKILA has also been shown to regulate T-cells activation by inhibiting NF-κB activity, and ectopic expression of NKILA in tumor-specific CTLs and TH1 cells correlated with apoptosis and shorter patient overall survival." (PMID 32194993, 2020). "NKILA is reported to preferentially sensitize antitumor T cells to cell death upon activation by tumor antigens." (PMID 32083005, 2020). "LncRNA NKILA was shown to indict shorter overall survival of hepatocellular carcinoma patients and enhance the anti-tumor effects of baicalein in tumor cells through modulating NF-κB signaling." (PMID 32269179, 2020). "In this study, we demonstrated that NKILA was down-regulated in HCC tissues and cell lines, and decreased NKILA expression was significantly associated with larger tumor size and positive vascular invasion in HCC patients." (PMID 32015685, 2020). "In summary, a higher expression level of lncRNA NKILA exhibited a close relationship with poorly distinguished grade, deep tumor invasion, and lymph node metastasis." (PMID 32851072, 2020). "LncRNA NKILA causes activation-induced cell death (ACID) in tumor-specific cytotoxic T lymphocytes (CTLs) and type 1 helper T (TH1) cells to promote tumor immune evasion by inhibiting the NF-κB signaling pathway via interaction with p65 and IkBa." (PMID 33050646, 2020). "LncRNA NKILA, known as nuclear factor-κB (NF-κB)-interacting lncRNA (NKILA), can improve the sensitivity of tumor-specific CTLs and type 1 helper T (TH1) cells, resulting in AICD by inhibiting NF-κ B activity." (PMID 31850199, 2019). "NKILA overexpression in S18 cells greatly inhibited the tumor growth (P < 0.001), demonstrating that downregulation of NKILA is required for the malignant transformation of nasopharyngeal epithelial cells." (PMID 31430288, 2019). "Low expression of NKILA was correlated with metastasis (P < 0.05), larger tumor size (P <0.05), and late clinical stage of NPC patients (P < 0.005)." (PMID 31430288, 2019). "By a series of in vitro and in vivo experiments, we show that NKILA exerts its effect as a tumor suppressor via inhibiting tumorigenesis and metastasis of NPC." (PMID 31430288, 2019). "Nuclear Factor-κB Interacting LncRNA (NKILA), encoded by the gene located on chromosome 20q13, has been reported to be down-regulated in TSCC tissues and the tissue samples with high tumor node metastasis (TNM) stage." (PMID 29416703, 2018).
tumor (continued). "As NKILA is associated with NF-κB, NF-κB inhibitor (Bay-117082 or JSH-23) can inhibit tumor cell metastasis." (PMID 29416703, 2018). "Similar to MALAT1, NKILA is another lncRNA that regulates TLR4 signaling and restrains NFκB activation; NKILA is induced by LPS in tumor cells and interacts with the NFκB/IκB complex, preventing its phosphorylation by IKKs and subsequent NFκB activation." (PMID 30515175, 2018). "Low NKILA expression correlated with large tumor size and advanced TNM stage, and predicted poor overall and disease-free survival of ESCC patients." (PMID 29348395, 2018). "Either high expression of HOTTIP, LINC00152, LINC00673, MALAT1 and UCA1, or low expression of AC007392.4, MEG3 and NKILA is found in tumor tissues." (PMID 29416703, 2018). "In this study, we focused on the newly identified lncRNA NKILA and found that NKILA was significantly downregulated in the ESCC tumor tissues compared with corresponding normal tissues." (PMID 29348395, 2018). "Down-regulated NKILA or highly expressed MALAT1 and UCA1 are associated with tumor metastasis, especially lymph node metastasis." (PMID 29416703, 2018). "We used fold change of NKILA (tumor/matched normal tissues) as the expression level of each patient and found that 54.01% of ESCC patients showed decreased expression (Fold change < 1) of NKILA." (PMID 29348395, 2018). "In the subcutaneous mouse model, enforced NKILA expression significantly suppressed tumor growth, which was consistent with the in vitro results." (PMID 29348395, 2018). "Further loss- and gain-of-function assays indicated that NKILA inhibited proliferation and migration of ESCC cells in vitro, suppressed tumor growth and lung metastasis in vivo." (PMID 29348395, 2018). "We performed loss- and gain-of-function assays to investigate the role of NKILA in tumor cell malignant behavior." (PMID 29379981, 2018). "The results showed that the expression of NKILA was significantly downregulated in tumor tissues compared with the adjacent normal tissues in these 106 NSCLC patients (p < 0.001)." (PMID 28412955, 2017). "These 106 patients were classified into high (n = 53) or low (n = 53) expression of NKILA based on median value of NKILA in tumor tissues." (PMID 28412955, 2017). "We measured the expression of NKILA in paired tumor tissues and matched adjacent normal tissues from 106 patients with NSCLC using qRT-PCR." (PMID 28412955, 2017). "The present study found that the expression of NKILA was downregulated in tumor tissues of NSCLC, which improved the metastasis of NSCLC patients." (PMID 28412955, 2017). "In summary, our present findings further proves that NKILA plays vital roles in controlling tumor cell migration and invasion by blocking the phosporylation of IκB, NF-κB activation and the following EMT process." (PMID 27613832, 2016). "In this study, we aimed to investigate the role of NKILA in regulating the NF-κB activity, tumor cell EMT and metastasis in TSCC, as well as the clinical significance of NKILA in predicting tumor metastasis and patient prognosis." (PMID 27613832, 2016). "And low NKILA expression in TSCC is significantly correlated with tumor metastasis and poor patient prognosis." (PMID 27613832, 2016). "Consistent with the in vitro study, NKILA negatively control the tumor metastasis in experimental metastasis model." (PMID 27613832, 2016). "Tscca-vector cells and CAL27-shNKILA cells were more prone to develop lung metastasis with H&E staining of large amount of tumor cells, while Tscca-NKILA and CAL27-shGFP cells were less efficient to form metastasis." (PMID 27613832, 2016). "By univariate analysis, the variables clinical stage (P < 0.001), tumor size (P = 0.001) and NKILA expression level (P < 0.001) were found to be significantly associated with prognosis." (PMID 27613832, 2016). "NKILA is transcriptionally induced in tumor-infiltrating CTLs upon T-cell receptor stimulation." (PMID 41409273, 2025).
tumor (continued). "Meanwhile, high NKILA levels were detected in tumor tissues (p < 0.01)." (PMID 41498025, 2025). "Notably, the transcription of NKILA is regulated by calmodulin-induced histone acetylation and STAT1 signaling, and the high levels of NKILAhi tumor-specific CTLs are associated with poor survival in BC patients." (PMID 37342324, 2023). "A study on non-small cell lung cancer showed downregulated NKILA in tumor samples." (PMID 36770654, 2023). "NKILA lncRNA promotes tumor immune escape by sensitizing T cells to activation-induced cell death." (PMID 35249533, 2022). "Collectively, NKILA was a tumor suppressor lncRNA frequently hypermethylated in DLBCL." (PMID 35052468, 2022). "In the third, 5-methylcytosine and METTL3-mediated m6A modification of lncRNA NKILA could accelerate the tumor growth and metastasis of CCA." (PMID 36476503, 2022). "LncRNA NKILA activates T cell‐induced cell death to promote tumor immune escape." (PMID 34374227, 2021). "Moreover, NKILA silencing in metastatic tumor infiltrating lymphocytes and CAR T cells can overcome tumor immune escape and improve the efficacy of adoptive T cell therapy in cancer treatment." (PMID 34295338, 2021). "Four lncRNAs—NKILA, AC005520.2, AC245884.8, and AL354836.1—were age-related, four lncRNAs—MIR4435-2HG, NKILA, AL591845.1, and AC005520.2—were associated with tumor stage, and six lncRNAs—MIR4435-2HG, ELFN1-AS1, NKILA, AL591845.1, AC005520.2, and AL354836.1—were associated with TNM stage." (PMID 33750326, 2021). "Moreover, decreasing the levels of NKILA significantly prolonged the median survival time of tumor-bearing nude mice, and the median survival time of LN229-20(S)-Rg3 tumor-bearing nude mice was significantly longer than that of LN229-control mice." (PMID 32382013, 2020). "In the patient-derived xenograft (PDX) model, CD8+ T cells transfected with NKILA shRNA were implanted into immunocompromised mice, which effectively inhibited the tumor growth and overcame tumor immune evasion by increasing infiltration and cytotoxicity of CLTs and decreasing the AICDs." (PMID 33148302, 2020). "Furthermore, NKILA endorses tumor immune evasion via inducing T cells to activation-mediated cell death." (PMID 32878637, 2020). "Therefore, NKILA acts as a tumor suppressor, and low levels of NKILA in patients predict poorer clinical outcomes." (PMID 32382013, 2020). "In addition, to explore the role of NKILA in tumorigenesis in vivo, xenograft tumor experiments were performed." (PMID 31430288, 2019). "S18 cells overexpressing NKILA or carrying a control vector were injected subcutaneously into the flank of nude mice, and then we measured the tumor size every 2 days to calculate the tumor volume." (PMID 31430288, 2019). "Second, we showed that NKILA expression decreased significantly with advanced disease staging in NPC clinical tissue samples, further research showed low expression of NKILA was correlated with metastasis (P< 0.05), larger tumor size (T stage, P <0.05), and late clinical stage (TNM stage, P < 0.01)." (PMID 31430288, 2019). "In addition, NKILA exerts its effect as a tumor suppressor via inhibiting tumorigenesis and metastasis of NPC, and overexpressing NKILA reverses tumorigenesis and metastasis of NPC." (PMID 31430288, 2019). "Our functional experiments showed that NKILA could function as a tumor suppressor through inhibition of cell proliferation and migration in vitro and in vivo." (PMID 29348395, 2018). "In the present study, we found that NKILA expression was decreased in advanced ESCC tumor tissues and that NKILA inhibited ESCC cell metastasis in vitro and in vivo and thus compliments the complicated networks through which TGF-β signaling regulates cancer progression and metastasis." (PMID 29379981, 2018). "Protein level of IκBα and NKILA expression level correlated inversely in ESCC tumor tissues." (PMID 29348395, 2018). "Moreover, NKILA expression levels are decreased in the advanced tumor tissues of patients with ESCC." (PMID 29379981, 2018).